Y_RNA (Y RNA )
Gene: Miscellaneous RNA gene on chromosome 1 (8,328,067 to 8,328,179, forward strand). Ensembl gene ENSG00000252254.
Homologues: Orthologues: macaque Y_RNA (92% identical), mouse Gm56393 (66% identical). Paralogues in human: RNY1 (88% identical), Y_RNA (86% identical), Y_RNA (84% identical), RNY1P11 (83% identical), Y_RNA (83% identical), Y_RNA (82% identical), RNY1P8 (81% identical), Y_RNA (81% identical), Y_RNA (80% identical), RNY1P5 (79% identical), Y_RNA (79% identical), RNY1P10 (78% identical), and 94 more.